EFNB1 (ephrin B1)
Diseases named in the same sentence as EFNB1 in open-access papers (continued):
Sharing a sentence is not in itself a finding about the gene and the disease.
tumor (continued). "Functionally, ephrin-B1 modulates multiple pathways, including p38, MSK1/2, Stat1/2/4/5a/6, and paxillin, following ligand stimulation or EphB2 inhibition, suggesting broad influence over tumor behavior." (PMID 41200151, 2025). "EFNA5, EFNB1 and EFNB2 were found highly expressed in tumor tissues of ESCA." (PMID 37160815, 2023). "EphB1 is co-expressed with genes such as ephrin-B1, RND1/2, and SEMA3A, key regulators of neuronal migration, synaptogenesis, and axonal development, indicating that neurodevelopmental pathways may be hijacked to support tumor growth." (PMID 41200151, 2025). "The expression of EFNB1 is significantly higher in HCC tissues than in nontumor tissues and contributes to tumor progression in vivo by promoting neovascularization in HCC." (PMID 36052169, 2022). "Moreover, we have designed and purified both glycosylated and nonglycosylated EFNB1-RBD-Fc recombinant proteins, subsequently examining their antitumor efficacy as well as their influence on the tumor microenvironment." (PMID 39864628, 2025).
cancer (22 papers, 2003 to 2025). A tumor composed of atypical neoplastic, often pleomorphic cells that invade other tissues. "Ephrin-B1 associates physically with TJ proteins claudin-1 or claudin-4, promoting ephrin-B1 phosphorylation, and affecting cell–cell adhesion in cancer cells." (PMID 38534339, 2024). "Ephrin-B1 binds AJ component Pick1, and overexpression of the former phenocopies the loss of the latter, both resulting in the dissociation of cancer epithelial cells via disruption of the AJs." (PMID 38534339, 2024). "A plethora of studies have implicated EFNB ligands in cancer cell biology, and several studies report paradoxical effects of EFNB1, EFNB2, and EFNB3 ligands." (PMID 35565468, 2022). "Furthermore, we found a significant positive association between EFNB1 and different immune response cells toward cancer, such as B cells, CD4+ T cells, CD8+ T cells, neutrophils, macrophages, and DCs." (PMID 36052169, 2022). "A recent study has implicated TUBB4B as an essential factor required for the maintenance of cancer stem cell niche via its interaction with Ephrin-B1." (PMID 37784035, 2023). "We also found that the expression of EFNB1 was positively related to most immune and stromal cells in HCC tissues, such as cancer-associated fibroblasts, myeloid dendritic cells, and M2 macrophages." (PMID 36052169, 2022). "This pre-clinical study identified a novel pain cascade involving the release of IL-1β from a cancer-inoculated region, induction of ephrin B1 gene expression in DRGs, and subsequent enhancement of tyrosine phosphorylation of NR2B in the spinal cord." (PMID 20979661, 2010). "We have identified a novel pain cascade, in which IL-1β production in cancer-inoculated regions induces ephrin B1 gene expression in DRGs and then ephrin B1 enhances the tyrosine phosphorylation of NR2B via Eph B receptor in the spinal cord." (PMID 20979661, 2010). "Devazepide (10 mg/kg) was administered orally once a day from day 7 to 14 after transplantation, and gene expression of ephrin B1 and the Eph B1 receptor in L4-5 DRGs and the amount of IL-1β protein in the cancer-inoculated region were then measured." (PMID 20979661, 2010). "Repeated administration of Z-360 suppressed the gene expression of ephrin B1 by 70.7% compared with the vehicle-treated group in cancer-induced pain mice (p < 0.001)." (PMID 20979661, 2010). "In this cascade, IL-1β production from cancer-inoculated regions induces the gene expression of ephrin B1 in DRGs, which then ephrin B1 enhances the tyrosine phosphorylation of NR2B via Eph B receptor in the spinal cord, finally leading to pain." (PMID 20979661, 2010). "Here, we examined the effects of devazepide on ephrin B1 gene expression in DRGs and the level of IL-1β in the cancer-inoculated region in the cancer-induced pain model in mice." (PMID 20979661, 2010). "Here, devazepide (10 mg/kg) reduced the level of IL-1β protein in cancer-inoculated regions, and significantly suppressed the gene expression of ephrin B1 in DRGs to a similar degree as Z-360." (PMID 20979661, 2010). "We demonstrated that IL-1β increased in cancer-inoculated regions and induced the expression of the ephrin B1 gene in the periphery of DRGs." (PMID 20979661, 2010). "Z-360 was found to inhibit this pain cascade, suggesting that Z-360 reduces cancer-induced pain through the suppression of IL-1β production in cancer-inoculated regions, which in turn inhibits ephrin B1 gene expression, and tyrosine phosphorylation of NR2B." (PMID 20979661, 2010). "In a mouse model of cancer-induced pain, ephrin B1 gene expression in dorsal root ganglia (DRGs) and the phosphorylation of NR2B in the spinal cord were induced." (PMID 20979661, 2010). "Ephrin-B1 (also known as lerk-2, stra-1 and cek5-L), which is the ligand for hek5, hek10 and elk, is strongly upregulated by RA in mouse P19 embryonal carcinoma cells and D3 embryonic stem cells." (PMID 12671705, 2003).
cancer (continued). "In addition, the intracellular C-terminus of ephrin-B1, which was necessary to cancer invasion, was reported to manage the MMP8 liberation from cells through activating the cell trafficking regulator Arf1." (PMID 35884594, 2022). "Similarly, EFNB1 expression was significantly higher in cancer tissues than in paired adjacent normal tissues (p = 0.0012)." (PMID 36052169, 2022). "For example, studies have reported that exosomes from HNSCC tumors could induce axonogenesis by the exosome-packaged axonal guidance molecule, ephrin B1, which could promote the metastasis and progression of cancer." (PMID 35873456, 2022). "EFNB1 stimulates the secretion of matrix metalloproteinase-8, which promotes cancer cell invasion." (PMID 34824583, 2021). "Here, we investigated the mechanism of analgesic action of Z-360 in a severe cancer-induced pain model in mice, which is considered to be opioid-resistant, by examining ephrin B1 gene expression, N-methyl-D-aspartate receptor NR2B subunit phosphorylation, and interleukin-1β (IL-1β) production." (PMID 20979661, 2010). "To investigate the effects of increased gene expression of ephrin B1 in the mouse model of cancer-induced pain, we examined the change in the inflammatory mediator IL-1β in the cancer-inoculated region of the right hind paw by double sandwich enzyme-linked immunosorbent assay (ELISA)." (PMID 20979661, 2010). "The repeated administration of devazepide significantly suppressed the expression of the ephrin B1 gene compared with the vehicle-treated group in cancer-induced pain mice (p < 0.01); however, the gene expression of the Eph B1 receptor was unchanged in all of the test groups." (PMID 20979661, 2010). "The remaining nine surface proteins identified solely (ANTXR1, AG1, DCBLD2, EFNB1, EMB, OSMR, SLC1A5) or found upregulated (ATP1B3 and ITGB1) on the MCF10A surface had no direct association with embryonic development signaling in the context of KRas mutant signaling in cancer cell lines." (PMID 27894102, 2016). "Recent studies have shown that cancer cells express neurotrophic markers such as NGF, BDNF, and GDNF and release axon guidance molecules such as Ephrin B1 to promote axonogenesis, neurogenesis, and neuronal reprogramming." (PMID 38920662, 2024). "Despite this general qualitative increase in expression, there are quantitative differences: ephrin-B1, B2, and A5 are far more highly expressed in invasive and metastatic samples than in DCIS, and the frequency of ephrin-B3 expression in all cancers seems to be lower than the other ligands." (PMID 34360867, 2021). "EFNB1 interacts with CNK1 to promote cell migration by activating JNK, which may have an important function in cancer metastasis." (PMID 34824583, 2021). "In summary, we have identified a novel pain cascade, IL-1β (cancer-inoculated region) → ephrin B1 (DRGs) → NR2B (spinal cord) → pain, that may be responsible for the development of opioid-resistant pain in the mouse model of cancer-induced pain." (PMID 20979661, 2010). "Moreover, we observed that the CCK1 receptor antagonist devazepide similarly suppressed up-regulation of ephrin B1 gene expression and IL-1β production, and that the intraperitoneal injection of sulfated CCK-8 induced the production of IL-1β in the cancer-inoculated region." (PMID 20979661, 2010). "In addition, EFNB1 and NGFR were downregulated in CD44+ cancer cells versus normal cells." (PMID 26673618, 2016).
infection (5 papers, 2017 to 2025). The state of being infected such as from the introduction of a foreign agent such as serum, vaccine, antigenic substance or organism. "The infection rates in both the ephrin B2 KD clone#2 and the ephrin B1/B2 dKD cells were significantly reduced compared to the control cells." (PMID 40285015, 2025). "This included three receptor–RBP pairs for which mRNA levels were significantly associated with infection in the analyses (Cedar–EFNB1, Lujo–NRP2 and LCMV–DAG1), versus four with no apparent association (HCV–SCARB1, Cedar–EFNA2, SFTSV–MYH9 and rabies–NCAM1)." (PMID 39747691, 2025). "Interestingly, while the FOXO3 sense mRNA remains unaltered upon EYFP-ICP4 infection, levels for the EFNB1 mRNA showed a twofold increase." (PMID 29089033, 2017). "Similarly, infection with the Cedar virus pseudotype was positively associated with the expression of EFNB1 and EFNB2 (P < 0.01), but not of EFNA2 or EFNA5." (PMID 39747691, 2025). "Confirming the results obtained with omics data, only EFNB1 and NRP2 overexpression increased infection by Cedar and Lujo pseudotypes, respectively." (PMID 39747691, 2025). "Meanwhile, cells expressing sEFN A1 or A5 showed no signs of infection or morphological changes, further confirming EFNB2 and EFNB3 as the primary receptors critical for viral entry, whereas EFNB1 may possess a conditional, auxiliary role in mediating viral entry." (PMID 40872782, 2025).
adenocarcinoma (1 paper, 2021). A common cancer characterized by the presence of malignant glandular cells. "Lastly, ephrin-B1 expression was reported more frequent in poorly differentiated adenocarcinomas than well-differentiated ones." (PMID 34445116, 2021).
proliferative retinopathy (1 paper, 2024). "The goal of this study was to develop a mouse model of a human-type disease (rodents do not develop proliferative retinopathy), with a focus on Ephrin B1." (PMID 38501146, 2024).
EFNB1 also shares sentences with these, for which no sentence is quoted: frontonasal dysplasia (4 papers); Arthritis (2); cleft lip (2); Strabismus (2); adenoma (1); aortic aneurysm (1); atherosclerosis (1); B-cell lymphomas (1); brain disorder (1); CHARGE syndrome (1); colitis (1); colorectal adenocarcinoma (1); Coronal craniosynostosis (1); COVID-19 (1); diaphragmatic hernia (1); ependymoma (1); epilepsy (1); genetic disorder (1); heart failure (1); hepatocellular carcinoma (1); hyperlipidemia (1); hypogonadism (1); Intellectual disability (1); Kallmann syndrome (1); multiple sclerosis (1); neurodegenerative disease (1); neurofibromatosis type 1 (1); non-small cell lung carcinoma (1); Nystagmus (1); Opitz G/BBB syndrome (1).
A further 9 diseases each share a sentence with EFNB1 in 1 paper.